HMGB1 (high mobility group box 1)
Diseases named in the same sentence as HMGB1 in open-access papers (continued):
Sharing a sentence is not in itself a finding about the gene and the disease.
tumor (continued). "Immunogenic cell death depends on the alarmin high mobility group protein B1 (HMGB1) as it binds nucleic acids released from dying tumor cells in the DC endosome, facilitating innate sensing of dead tumor cell nucleic acids." (PMID 35784290, 2022). "Therefore, HMGB1 may be involved in the generation of tumor radio-resistance." (PMID 36260180, 2022). "Mechanistic studies reveal that anti‐PD‐L1‐DOX‐R848‐MIP‐3α/TKNP specifically targets tumor tissue, resulting in maximum exposure of calreticulin (CRT) and HMGB1 in tumors, and significantly enhances intratumoral infiltration of CD4+ and CD8+ T cells in tumors." (PMID 37693071, 2022). "We analyzed the expression of HMGB1 and RAGE in ESCC samples and adjacent tissues located around the tumor tissue, subsequently ascertained the correlation between the HMGB1 and RAGE expressions and clinicopathologic parameters." (PMID 35829833, 2022). "Several DAMPs, such as HMGB1, heat shock proteins, ATP, CRT and S100 proteins, have been reported as promoting tumor progression via PAMP activation and advanced glycation end-product (RAGE) receptors, including the activation of immunosuppressive cells." (PMID 36142453, 2022). "The alarmin-1 protein (high-mobility group box 1, HMGB1), in addition to secretion by macrophages and monocytes, is secreted by dead tumor cells formed due to necrotic processes and therapeutic effects." (PMID 36140182, 2022). "The combination of HMGB1 with Toll-like receptors and RAGE leads to the activation of nuclear factor-κB (NF-κB) and concurrently increases angiogenic factor production, tumor tissue destruction, and further promotes the inflammatory response." (PMID 36466838, 2022). "Except for inducing cell death, some inflammatory factors that are produced by pyroptosis, such as IL-1β, IL18, and HMGB1, can activate the cancer-promoting signaling pathways including MAPK and VEGF pathways, which accelerates tumor growth." (PMID 35000541, 2022). "Remarkably, tumors from DOC-treated mice showed advanced expression of high-mobility group box 1 (HMGB1) and CXCL11, raised HER2-CAR T cell infiltration as well as tempered tumor progress." (PMID 35093187, 2022). "Research showed that miR-449a suppresses tumor growth, migration, and invasion in NSCLC by targeting the HMGB1-mediated NF-κB signaling pathway." (PMID 36523419, 2022). "The expression of HMGB1 and TLR4 was significantly high in tumor tissue compared with that in normal tissue, the expression of CCL28, KLF2 and TNFSF18 in tumor were similar to normal tissues." (PMID 36204682, 2022). "The interaction of HMGB1 with T cell immunoglobulin mucin–3 (TIM-3), an immunoregulatory protein, induces the secretion of VEGF, which promotes tumor angiogenesis." (PMID 36359780, 2022). "In the xenograft model of SAS cells in nude mice, HMGB1 was detected in plasma 3 days post-BNCT irradiation, even when the tumor regression started." (PMID 35336794, 2022). "HMGB1, which acts as a ligand of RAGE, has been shown to participate in glioma tumor cell proliferation by activating the NF-κB pathway and promoting IL-8 secretion." (PMID 36384979, 2022). "The best outcome is probably due to the release of HMGB1, which stimulates the maturation of dendritic cells (DCs) through the activation of TLR4, and the subsequent recruitment of TIL into the tumour." (PMID 34194625, 2021). "To directly evaluate the correlation between the lncRNA MIAT/HMGB1/IL6 axis and tumor resistance in NPC patients, we collected samples from cisplatin-sensitive patients and the patients developed resistance." (PMID 34094941, 2021). "HMGB1 and ATP are DAMPs of ICD that accelerate phagocytosis of dendritic cells and promote tumor antigen presentation to T cells." (PMID 34641524, 2021). "NDV infection also induces a strong ICD in lung and glioblastoma cancer cells, observable by the elevated exposure of calreticulin, the release of HMGB1, ATP, and HSP79/90, and the induction of a long-term tumor-specific immune response." (PMID 34745965, 2021).
tumor (continued). "However, our study proposed that SYVN1 may be a tumor suppressor that target HMGB1 for degradation." (PMID 34820329, 2021). "We also analyzed the expression of HMGB1 and DRP1 in NSCLC using the DriverDBv3 database (tumor parts (TP), tumor recurrent (TR) tissues, and normal tissues (NT))." (PMID 33807275, 2021). "We obtained four sensitive tumor samples and four resistant tumor samples and analyzed the expression levels of lncRNA MIAT, HMGB1, and IL6." (PMID 34094941, 2021). "Necrosis can release cancer-promoting factors like MMP1, HMGB1, and ICAM1, which induce microenvironment changes resulting in tumor aggressiveness." (PMID 34084172, 2021). "Using the HMGB1 and RICTOR-manipulated cell lines we found that downregulation of HMGB1 and RICTOR mRNAs significantly inhibited tumor spheroid growth and cell proliferation in vitro." (PMID 34916485, 2021). "Apoptotic tumor cells can express a large amount of calreticulin (CRT) on the surface of DCs and release HSPs and HMGB1, which can effectively fight against IL-10 or TGF-β, which have a negative regulatory effect." (PMID 34588987, 2021). "Our former data reveal that the tumor-promoting protein HMGB1 was involved in regulation of autophagy via AMPK/mTOR signaling and verified anti-HCC effects of HMGB1 inhibition accounted for autophagy induction." (PMID 33747917, 2021). "It has been reported that miR-34a influenced tumour biological activities by targeting several genes or signal pathways, such as CCND1 in EC, PDGFR in GC, HMGB1 in CRC, and XIST in PC." (PMID 33446130, 2021). "In syngeneic mice, tumor growth was accompanied by elevated circulating WBC, sP-selectin, TGF-β1, exosomes, and exosomal HMGB1, along with tumor HMGB1 and CD42b." (PMID 33669632, 2021). "AIMS(PTX) treatment of the 4T1 tumor cell line successfully induced the exposure of CRT and the release of HMGB1, which showed that ICD was induced effectively." (PMID 34363349, 2021). "HMGB1 and DRP1 expression in tumor tissues were evaluated using qPCR, WB, and immunohistochemistry (IHC)." (PMID 33807275, 2021). "Various DAMPs are released after induction of these pathways such as HSPs, HMGB1 and CRT and infection of tumor cells has been shown to improve the T cell-mediated anti-tumor immune response in tumor-bearing mice." (PMID 34141622, 2021). "A synergy of HMGB1 and TLR9 was shown to up-regulate mitochondrial biogenesis of HCC cell lines and in murine HCC models under hypoxic conditions, promoting tumor survival and proliferation." (PMID 34025657, 2021). "Circulating HMGB1 promotes dendritic cell maturation and activation via Toll-like receptor 4 (TLR4), which facilitates the cross-presentation of shed tumor antigens by dendritic cells to activate tumor-specific cytotoxic T cells." (PMID 33799527, 2021). "We have postulated that the release from dead cells of both ‘find-me’ (ATP) and danger signals (HMGB1 and HSP90) is enough to support robust immune responses, whereas when only one of the adjuvants concurs, anti-tumor immunity fails." (PMID 34485114, 2021). "HMGB1 and VEGF-D are involved in tumor lymphangiogenesis, and VEGF-C and VEGF-D are also essential members of the VEGF family." (PMID 34456716, 2021). "In vivo study confirmed the cachexia effects of HMGB1 and anti-cachexia effects of glycyrrhizin on CT26 tumor-bearing mice." (PMID 34867338, 2021). "The interplay between HMGB1 and TLR4 contributed to platelet activation and tumor spreading in mice bearing with melanoma and Lewis lung carcinoma." (PMID 34722319, 2021). "Our results indicate that HMGB1 signalling between EAC cells and macrophages creates an inflammatory tumour microenvironment to facilitate EAC progression." (PMID 33922955, 2021).
tumor (continued). "It has been shown that cyclophosphamide analogues improved tumor immunogenicity by facilitating the release of ICD markers (CRT, HMGB1, and ATP)." (PMID 35069604, 2021). "High-mobility group box 1 (HMGB1), a nuclear chromatin-binding protein, displays tumor-promoting effects in malignancies." (PMID 33669632, 2021). "It was reported that treatment with anti-platelet drug, dipyridamole and aspirin inhibited tumor progression in Lewis lung carcinoma (LLC) cell lines and reduced the exosomal HMGB1 content." (PMID 34721407, 2021). "In vitro experiments showed that anthracyclines promote ICD in tumor cells by inducing the translocation of calreticulin, HSP70 and 90 to the cell surface and promoting HMGB1 release." (PMID 34025657, 2021). "The effects of GW4869 in tumor-bearing mice were paralleled by a reduction of circulating WBC, sP-selectin, TGF-β1, exosomes, and exosomal HMGB1." (PMID 33669632, 2021). "Beyond the controversy of HMGB1, the roles of HMGB2/3 in cancers are unclear, especially in the context of the tumor immune microenvironment (TIME)." (PMID 34777483, 2021). "Specifically, following histotripsy treatment of cancer spheroids, HMGB1, CRT, and HSP were identified in cell supernatants and correlated to levels expected from within the tumor after an in vivo ablation." (PMID 34136405, 2021). "Immunologic cell death markers, such as high mobility group box 1 (HMGB1) and soluble receptor for advanced glycation end products (sRAGE), inducers of PD-L1 in tumor cells, are increased by TACE in HCC patients." (PMID 34575463, 2021). "Among the DAMPs, HMGB1 release and CRT re-localization has been established in BC following exposure of human tumor cells in vitro, but also in vivo in patients treated with doxorubicin or paclitaxel." (PMID 34885109, 2021). "What is more, tumor grades of HNSC were significantly increased with the elevation of HMGB expression, while an opposite trend was observed for HMGB1 expression in KIRC." (PMID 34777483, 2021). "The primary novelty of this work is the discovery that the autocrine and paracrine HMGB1/RAGE/NF-κB signaling is a key mechanism for upregulation of PD-L1 and PD-1 in the tumor cell-TAM interaction, which can be activated by Nano-DOX." (PMID 34488792, 2021). "Chondroitin sulfate and heparan sulfate strongly bind to RAGE and suppressed the colonization of lungs by tumor cells, and GM-1111 inhibited interactions between RAGE and CML, HMGB1, and S100B and exhibited anti-inflammatory activity." (PMID 34199060, 2021). "In examining the dissected tumor tissues, both dipyridamole and GW4869 decreased protein contents in cyclin D1, β-catenin, YAP1, Runx2, phosphorylated Smad2/3, HMGB1, RAGE, and CD42b, except the TLR4." (PMID 33669632, 2021). "S100-derived peptide (ELKVLMEKEL) was found to compete for the RAGE site required for binding ligands, such as S100P, S100A4, and HMGB1, and reduced RAGE-mediated NF-κB activation, inflammation, tumor growth, and metastasis in different cancer cells." (PMID 34199060, 2021). "Gold compounds support cancer cell antigenicity and promote anti-tumor immune response by inducing the release of CRT, ATP, HMGB1, HSP, and NKG2D to enhance immunogenicity." (PMID 34588987, 2021). "Amino acids 150–183 of HMGB1 are responsible for binding to RAGE for invasive migration and growth of tumor cells through the activation of p38 MAPK and Erk1/2." (PMID 33807604, 2021). "The cancer cell survival suppressive effect of dipyridamole was paralleled by a reduction of the HMGB1/RAGE axis, and proliferation- and migration-related β-catenin, YAP1, Runx2, TGFβ1/Smad, and cyclin D1 in in vitro and in vivo tumor growth models." (PMID 33669632, 2021). "cDAMPs act as “find me” signals (ATP and HMGB1) or “eat me” signals (HSPs and CRT) to mobilize antigen-presenting cells (APCs) such as dendritic cells (DCs), macrophages, and their precursors to tumor cells with the help of chemokines." (PMID 34489957, 2021).
tumor (continued). "The OS was further improved when patients were treated with neoadjuvant CRT, indicating that both tumor intrinsic and neoadjuvant CRT contribute to increased HMGB1 levels." (PMID 33920544, 2021). "HMGB1 activates DCs, promoting their maturation and ATP release, leading to the enhancement of CD8+ effector T cells antigen presentation and their anti-tumor-specific activation." (PMID 34768644, 2021). "However, the mechanism of action of HMGB1 in regulating tumor mobility remains unclear." (PMID 33807275, 2021). "The production of high levels of HMGB1 by tumor cells per se, as well as by infiltrating inflammatory cells, favors the establishment of a highly immunosuppressive TME conducive to tumor cell proliferation and progression." (PMID 32664328, 2020). "In fact, DAMP proteins binding to TLR4 (e.g., HMGB1, S100, HSPs, API5, and RPS3) have been used as adjuvants for DC-based vaccines, affecting tumor prevention, treatment, and survival." (PMID 33299138, 2020). "Podoplanin (PDPN, tumor cells): CLEC-2 (platelet) and HMGB1 (tumor cells): TLR4 (platelets) are other adhesion protein-ligand pairs that support platelet activation and aggregation on tumor cells, and ultimately metastasis." (PMID 33042789, 2020). "Anti-tumor immune response can be primed by ICD, a type of cell death characterized by cell-surface translocation of CALR, extracellular release of ATP and HMGB1." (PMID 32455811, 2020). "HMGB1 protein and RAGE are identified as a ligand–receptor pair that plays an important role in regulating the invasiveness of tumor cells." (PMID 32698492, 2020). "The supernatants from dying Ad-TK + GCV-treated GL26 tumor cells indicated that TLR2-dependent NFκB activation was inhibited when tumor cells were treated with glycyrrhizin, an antagonist of HMGB1." (PMID 33299138, 2020). "HMGB1 and nucleic acids from apoptotic cells stimulate anti-tumor immunity, and TIM-3 can block this stimulation by competition for binding to the HMGB1-nucleic acid complex." (PMID 32656079, 2020). "TIM-3 interacts with numerous ligands including tumour-secreted galectin-9, high-mobility group protein B1 (HMGB1), carcinoembryonic antigen cell adhesion molecule 1 (CEACAM-1, expressed on tumour cells), and phosphatidyl serine (PtdSer)." (PMID 32645977, 2020). "We observed detectable increase of HMGB1 and CRT in the tumour from the group of PEG-TECM-NS/OLE, demonstrating that ICD was efficiently elicited." (PMID 33009382, 2020). "In addition, serum HMGB1 was significantly higher in patients who showed antigen-specific T cell responses compared with non-responsive patients, suggesting that the HMGB1 produced by chemoradiation plays an important role in inducing tumour antigen-specific T cells." (PMID 32246277, 2020). "The induction of NETosis involves mechanisms that are activated by HMGB1/TLR4 interactions and tumor-derived IL-8, respectively; NETs enhance tumor invasion via the presentation of proteolytic enzymes, such as MMP-9 and elastase." (PMID 32664328, 2020). "Further analysis of the pathological data and serum miR‐505 and HMGB1 expression found a close relationship among miR‐505, HMGB1, TNM staging, tumor size, and distant metastasis." (PMID 32348630, 2020). "Further, high-mobility group box 1 (HMGB1), released by dying tumor cells, interacts with TLR4 on platelets and mediates platelet–tumor cell interaction, which promotes metastasis." (PMID 32244723, 2020). "The licensing of DCs to process and present tumor antigens requires interaction of DAMPs (e.g., HMGB1, HSP70) released from dying tumor cells, with Toll-like receptor 4 (TLR4) on DCs." (PMID 32575843, 2020). "In fact, SK has been shown to induce the expression of different DAMPs including CRT, HMGB1, GRPp78, HSP70 and HSP90 in several tumor cell lines." (PMID 32656498, 2020). "HMGB1 mediates potent pro‐inflammatory effects by binding to TLR4 on DCs to stimulate efficient processing and cross‐presentation of tumor antigens from dying cells." (PMID 33179413, 2020).